CCDC177 (coiled-coil domain containing 177)
Synonyms: C14orf162; PLPL
Tractability: PROTAC: its protein half-life has been measured.
Gene: Protein-coding gene on chromosome 14 (69,569,799 to 69,574,871, reverse strand). Ensembl gene ENSG00000267909.
Subcellular location (Human Protein Atlas): Cytosol
Genetic constraint (gnomAD): Loss-of-function variants: 2 observed, 5.59 expected, observed/expected ratio (o/e) 0.36, 90% interval 0.14 to 1.12. That is too few expected variants to judge how well the gene tolerates losing a copy. Missense variants: 872 observed, 823.98 expected, observed/expected ratio (o/e) 1.06, 90% interval 1 to 1.12. Synonymous variants: 400 observed, 372.06 expected, observed/expected ratio (o/e) 1.08, 90% interval 0.99 to 1.17.
Homologues: Orthologues: chimpanzee CCDC177 (99% identical), macaque CCDC177 (98% identical), pig CCDC177 (92% identical), dog CCDC177 (91% identical), rat Ccdc177 (91% identical), guinea pig CCDC177 (91% identical), mouse Ccdc177 (91% identical).
Diseases named in the same sentence as CCDC177 in open-access papers:
CCDC177 is named in the same sentence as 3 diseases in open-access papers, as found by Europe PMC text mining. Sharing a sentence is not in itself a finding about the gene and the disease. The quoted sentences say what the papers report.
leiomyoma (1 paper, 2023). A well-circumscribed benign smooth muscle neoplasm characterized by the presence of spindle cells with cigar-shaped nuclei, interlacing fascicles, and a whorled pattern. "For comparison of differential expression of genes in leiomyomas, there was a significant race/ethnicity correlation in expression for TNFRSF19, IRS4, PLEKHG4B, PGR, KRT17, CCDC177, MYO5B, and ZNF703." (PMID 37686244, 2023).
lung squamous cell carcinoma (1 paper, 2024). "CCDC177 has been proven to have a significant prognostic value in patients with lung squamous cell carcinoma." (PMID 38715006, 2024).
CCDC177 also shares sentences with these, for which no sentence is quoted: Hyperglycemia (1 paper).